HADHA (hydroxyacyl-CoA dehydrogenase trifunctional multienzyme complex subunit alpha)
Description:
Mitochondrial trifunctional enzyme catalyzes the last three of the four reactions of the mitochondrial beta-oxidation pathway. The mitochondrial beta-oxidation pathway is the major energy-producing process in tissues and is performed through cycles of four consecutive reactions. Each beta-oxidation cycle shortens the fatty acyl-CoA by two carbons, yielding one acetyl-CoA (for the citric acid cycle), one FADH(2), and one NADH (which donate electrons to the respiratory chain for ATP production). These cycles repeat until the chain is fully degraded to acetyl-CoA units. Among the enzymes involved in this pathway, the trifunctional protein--responsible for the hydration, dehydrogenation, and thiolysis steps, shows specificity for long-chain fatty acids, such as those from dietary and stored fats. Mitochondrial trifunctional enzyme is a heterotetrameric complex composed of two proteins, the trifunctional enzyme subunit alpha/HADHA described here carries the 2,3-enoyl-CoA hydratase and the 3-hydroxyacyl-CoA dehydrogenase activities while the trifunctional enzyme subunit beta/HADHB bears the 3-ketoacyl-CoA thiolase activity (Probable). These activities have been experimentally confirmed on a few substrates derived from beta-oxidation of long-chain saturated fatty acids such as palmitate (hexadecanoate) and laurate (dodecanoate). In addition, based on its established catalytic mechanism, and combined genetic interaction or mutant phenotype evidence, it is predicted to act also on other substrates, including long-chain unsaturated fatty acids such as oleate (9Z-octadecenoate), linoleate (9Z,12Z-octadecadienoate), linolenate (9Z,12Z,15Z-octadecatrienoate), and others (Probable). Independently of subunit beta, HADHA also exhibits a cardiolipin acyltransferase activity that participates in cardiolipin remodeling; cardiolipin is a major mitochondrial membrane phospholipid. HADHA may act downstream of Tafazzin/TAZ, that remodels monolysocardiolipin (MLCL) to a cardiolipin intermediate, and then HADHA may continue to remodel this species into mature tetralinoleoyl-cardiolipin. Has also been proposed to act directly on MLCL; capable of acylating MLCL using different acyl-CoA substrates, with highest activity for oleoyl-CoA.
Synonyms: MLCL AT; LCEH; LCHAD; GBP; MTPA; ECHA; TP-ALPHA
Tractability: PROTAC: ubiquitination databases record sites on it; its protein half-life has been measured.
Target class: Enzyme; Oxidoreductase
Gene: Protein-coding gene on chromosome 2 (26,190,635 to 26,245,044, reverse strand). Ensembl gene ENSG00000084754.
Subcellular location: Mitochondrion; Mitochondrion inner membrane
Subcellular location (Human Protein Atlas): Mitochondria
Pathways (Reactome):
Metabolism: Acyl chain remodeling of CL; Beta oxidation of decanoyl-CoA to octanoyl-CoA-CoA; Beta oxidation of hexanoyl-CoA to butanoyl-CoA; Beta oxidation of lauroyl-CoA to decanoyl-CoA-CoA; Beta oxidation of myristoyl-CoA to lauroyl-CoA; Beta oxidation of octanoyl-CoA to hexanoyl-CoA; Beta oxidation of palmitoyl-CoA to myristoyl-CoA; mitochondrial fatty acid beta-oxidation of unsaturated fatty acids
Gene Ontology:
Molecular function: 3-hydroxyacyl-CoA dehydratase activity; enoyl-CoA hydratase activity; long-chain (3S)-3-hydroxyacyl-CoA dehydrogenase (NAD+) activity; long-chain fatty acyl-CoA hydrolase activity; protein binding; (3S)-3-hydroxyacyl-CoA dehydrogenase (NAD+) activity; acetyl-CoA C-acetyltransferase activity; catalytic activity; NAD+ binding; oxidoreductase activity; oxidoreductase activity, acting on the CH-OH group of donors, NAD or NADP as acceptor
Biological process: cardiolipin acyl-chain remodeling; fatty acid beta-oxidation; fatty acid metabolic process
Cellular component: mitochondrial fatty acid beta-oxidation multienzyme complex; mitochondrial inner membrane; mitochondrial nucleoid; mitochondrion
Genetic constraint (gnomAD): Loss-of-function variants: 21 observed, 39.72 expected, observed/expected ratio (o/e) 0.53, 90% interval 0.37 to 0.76. The upper end of that interval is the gene's LOEUF score, 0.76, which puts it in group 3 of 6, group 1 being the genes least tolerant of losing a copy. Missense variants: 417 observed, 513.14 expected, observed/expected ratio (o/e) 0.81, 90% interval 0.75 to 0.88. Synonymous variants: 188 observed, 200.7 expected, observed/expected ratio (o/e) 0.94, 90% interval 0.83 to 1.06.
Gene-disease validity (ClinGen):
ClinGen rates the evidence that HADHA causes each of these diseases.
long chain 3-hydroxyacyl-CoA dehydrogenase deficiency (autosomal recessive): Definitive.
Homologues: Orthologues: chimpanzee HADHA (99% identical), macaque HADHA (91% identical), rabbit HADHA (91% identical), dog HADHA (90% identical), guinea pig HADHA (89% identical), pig HADHA (89% identical), mouse Hadha (87% identical), rat Hadha (85% identical), tropical clawed frog hadha (75% identical), zebrafish hadhab (72% identical), zebrafish hadhaa (71% identical), Drosophila melanogaster Mtpalpha (56% identical), and 2 more. Paralogues in human: EHHADH (28% identical), HADH (13% identical), CRYL1 (9% identical).
Diseases named in the same sentence as HADHA in open-access papers:
HADHA is named in the same sentence as 121 diseases in open-access papers, as found by Europe PMC text mining. Sharing a sentence is not in itself a finding about the gene and the disease. The quoted sentences say what the papers report.
LCHAD deficiency (23 papers, 2014 to 2026). "Compound heterozygous HADHA variants can underlie isolated LCHAD deficiency; by contrast, compound heterozygous truncating or splice-disrupting variants in HADHA or HADHB more often cause complete MTP deficiency." (PMID 41155433, 2025). "The pathogenic HADHA variant c.1528G>C (p.Glu510Gln) is the predominant cause of LCHAD deficiency in Europe but is rare or unobserved in East Asian cohorts." (PMID 41155433, 2025). "Because LCHAD deficiency is inherited in an autosomal-recessive manner, it manifests only in individuals with pathogenic HADHA variants on both alleles." (PMID 41155433, 2025). "Isolated LCHAD deficiency due to the common mutation in HADHA, c.1528G>C (p.E510Q), is associated with a pigmentary retinopathy that can lead to vision loss and later onset neuropathy." (PMID 39088276, 2024). "LCHAD deficiency (LCHADD) is diagnosed when a mutation in the alpha subunit of mitochondrial trifunctional protein (HADHA) causes an isolated deficiency of LCHAD." (PMID 37834305, 2023). "The most common gene variant causing LCHAD deficiency is c.1528G > C p.(Glu510Gln) in the HADHA gene." (PMID 35782617, 2022). "MTP deficiency can be caused by either mutations in the HADHB gene or the HADHA gene, whilst LCHAD deficiency is only caused by mutations in the HADHA gene." (PMID 31730477, 2019). "Diagnosis of LCHAD deficiency was confirmed by molecular analysis of the HADHA gene revealing the prevalent mutation, c.1528G > C (p.E510Q), in a homozygous state." (PMID 30029694, 2018). "The most common MTP mutation is long-chain 3-hydroxyacyl-CoA dehydrogenase (LCHAD) deficiency caused by the c.1528G>C (rs137852769, p.Glu510Gln) substitution in exon 15 of the HADHA gene." (PMID 29095929, 2017). "Compound heterozygosity for the c.1528G>C and a second HADHA allele polymorphism may result either in isolated LCHAD deficiency or in general TFP deficiency." (PMID 41594271, 2026). "However, a homozygous variant (1528G>C) in HADHA has been reported to cause isolated LCHAD deficiency." (PMID 41480351, 2025). "Most frequent pathogenic variants in the HADHA gene associated with LCHAD deficiency." (PMID 41155433, 2025). "However, a recurrent c.1528G>C (p.E510Q) missense mutation in HADHA accounts for about 87% of the alleles reported in isolated LCHAD deficiency (MIM: 609016)." (PMID 39088276, 2024). "Similarly, a possibly damaging missense variant was identified in the gene HADHA, encoding the hydroxyacyl-CoA dehydrogenase, whose recessive gene defect causes pediatric long-chain 3-hydroxyacyl-CoA dehydrogenase deficiency." (PMID 39063061, 2024). "Moreover, the impact of HADHA and HADHB mutations found in patients with TFP/LCHAD deficiency on CL content or structure has only been cursorily investigated in isolated LCHAD deficiency due to the HADHA c.1528G>C (p.E510Q) mutation." (PMID 39088276, 2024). "Inborn defects affecting the MTP can translate in isolated long-chain-3-hydroxyacyl-CoA dehydrogenase (LCHAD) deficiency (generally associated with HADHA gene mutations), or in decreased levels of the three MTP-borne enzymes activities (generally associated with HADHB gene mutations)." (PMID 30925787, 2019).
cardiomyopathy (10 papers, 2017 to 2025). A disease of the heart muscle or myocardium proper. "Interestingly, HADHA deficiency has been associated with neonatal syndromes characterized by hypoglycemia, myopathy, and cardiomyopathy." (PMID 38724625, 2024). "The patient, described in a single case report, with pathogenic variants in HADHA, suddenly developed acute respiratory failure due to COVID-19 infection, accompanied by refractory hypotension from severe cardiomyopathy which led to multiple organ failure and death." (PMID 35955824, 2022). "Interestingly, the patient with two identified HADHA variants showed cardiac aortic valve insufficiency but not cardiomyopathy per se as in patients with one identified HADHA variant." (PMID 32999401, 2020).
hepatocellular carcinoma (7 papers, 2016 to 2024). A malignant tumor that arises from hepatocytes. "For example, miR-612 negatively controlled the formation of invadopodia, matrix degradation, and metastasis in hepatocellular carcinoma by involving HADHA-mediated lipid reprogramming." (PMID 34289835, 2021). "The level of HADHA in human renal cell carcinoma, breast cancer, and hepatocellular carcinoma is significantly downregulated." (PMID 32586350, 2020). "Clinically, the ATP synthase subunit and HADHA have been shown to be down-regulated in type 2 diabetes and hepatocellular cancer cells, respectively." (PMID 27507061, 2016). "Recent studies have also highlighted the potential of targeting the UBE2O/HADHA axis in the treatment of hepatocellular carcinoma (HCC), the most common primary malignant liver tumor and the sixth highest cause of cancer-related death." (PMID 39272922, 2024). "In hepatocellular carcinoma (HCC), miR-612 decreased invadopodia formation through HADHA-mediated cell membrane cholesterol alteration." (PMID 34290983, 2021).
mitochondrial trifunctional protein deficiency (7 papers, 2021 to 2025). "The initial workup identified metabolites suggestive of LC-FAOD and whole-exome sequencing (WES) identified a homozygous variant in HADHA gene, ultimately confirming the diagnosis of mitochondrial trifunctional protein deficiency (TFPD)." (PMID 41257106, 2025). "Mitochondrial trifunctional protein deficiency (MTPD) is diagnosed when mutations in HADHA or HADHB (a beta subunit of mitochondrial trifunctional protein) genes lead to a deficiency of all enzyme activities in the MTP complex." (PMID 37834305, 2023). "Mitochondrial trifunctional protein deficiency (MTPD) is a rare autosomal recessive disorder caused by pathogenic variants of HADHA or HADHB." (PMID 34712195, 2021). "HADHA and HADHB cause mitochondrial trifunctional protein deficiency (MTPD), leading to peroneal muscular atrophy." (PMID 34107874, 2021).
diabetes (6 papers, 2018 to 2025). "Our data indicated that HADHA may participate in TGF-β1-induced diabetes and is associated with DNA methylation that results in positive regulation." (PMID 30618784, 2018). "Our data point to a potential therapeutic strategy of targeting HADHA or the ketone body BHB for the treatment of diabetes." (PMID 35046401, 2022). "In conclusion, BHB is responsible for the inhibitory effect of HADHA on hepatic glucagon response, suggesting that HADHA activation or BHB elevation by pharmacological intervention hold promise in treating diabetes." (PMID 35046401, 2022). "In the mitochondria, HDAC3 facilitated HADHA deacetylation and induced aberrant mitochondrial FAO and injury, contributing to cardiac insult in diabetes." (PMID 40052435, 2025). "However, the pattern and composition of abnormal cardiolipin species in the case of the HADHA mutant and knockout cardiomyocytes were more specific than seen previously in heart failure or diabetes, suggesting that HADHA may be directly involved in cardiolipin processing." (PMID 32995760, 2020).
rhabdomyolysis (6 papers, 2018 to 2025). Necrosis or disintegration of skeletal muscle often followed by myoglobinuria. "Genetic data suggest an increased susceptibility to rhabdomyolysis in individuals of Japanese descent, due to specific mutations in genes involved in muscle metabolism, such as HADHA, HADHB, CACNA1S, and HLA-DRB1* 04:06." (PMID 40709115, 2025).
HELLP syndrome (5 papers, 2018 to 2024). A life-threatening condition that can potentially complicate pregnancy. "In particular, if the mother has a mutation in one copy of HADHA and the fetus has two copies of the HADHA mutation, the mother is more likely to have acute fatty liver of pregnancy (AFLP) and HELLP syndrome (hemolysis, elevated liver enzymes and low platelet count)." (PMID 32995760, 2020). "Finally, leveraging human-on-a-chip co-culture in vitro platforms, organ-organ lipid communication can be modeled to understand how, placental tissue lacking the HADHA gene may impact the health of a heterozygous mother’s liver to result in AFLP and HELLP syndrome." (PMID 32995760, 2020).
malignant lymphoma (5 papers, 2022 to 2025). "HADHA, which forms a heterodimer together with HADHB, is also widely up-regulated in malignant lymphomas, and down-regulation of HADHA can cause G0/G1 cell cycle arrest." (PMID 36106108, 2022). "Furthermore, the HADHA has been implicated in fostering ovarian cancer progression through the up-regulation of CDK1 and is identified as a potential risk factor for malignant lymphoma." (PMID 38637116, 2024). "Clinicopathological analysis showed that HADHA was the most frequently detected in malignant lymphoid tissue, and lowering the expression of TFPα could inhibit the expansion of malignant lymphoma cells, indicating that TFPα was a potential therapeutic target for malignant lymphoma." (PMID 36588702, 2022). "HADHA in lung carcinomas and both HADHA and HADHB in malignant lymphoma." (PMID 37601653, 2023). "Moreover, both HADHA and HADHB enzymes have been found overexpressed in malignant lymphoma progression, relying on fatty acid metabolism and notably FAO as a key metabolic pathway for tumor progression and survival." (PMID 37601653, 2023).
breast carcinoma (4 papers, 2012 to 2022). "First, although there is a strong circumstantial evidence that favors an inference of HADHA expression-breast cancer association, it must be realized that robust functional studies are required before this association can be conclusively claimed." (PMID 22240105, 2012). "Inclusion of those genes may not only affect the q values associated with HADHA but also may provide a more comprehensive understanding of the role of fatty acids in breast cancer." (PMID 22240105, 2012). "We next considered whether the association of HADHA gene expression with risk of breast cancer exhibited a threshold effect or whether it was a graded dose-response." (PMID 22240105, 2012). "Second, the k-means clusters (which explained 95.9% of the variability in HADHA expression) clearly demonstrated a dose-response association such that more severe down-regulation of HADHA was associated with a greater risk of being in the breast cancer group." (PMID 22240105, 2012). "Our results further support the putative involvement of HADHA in breast cancer susceptibility." (PMID 22240105, 2012). "This transformation indicated that there was an average 18.4% reduction in expression of HADHA (95% CI 4.5%-30.0%) in cases of breast cancer as compared to normal subjects." (PMID 22240105, 2012). "For example, Hsa_circ_0053063 is a circRNA generated from several exons of hydroxyacyl CoA dehydrogenase trifunctional multienzyme complex subunit alpha (HADHA), and it inhibits cell viability, proliferation, and progression of breast cancer through stabilization of PDCD4 by targeting miR-330-3p." (PMID 35795053, 2022). "Interestingly, a link between HADHA and cancer has previously been observed in breast cancer where the HADHA gene was significantly under-expressed in cancerous tissues, especially in tumors with estrogen receptor-negative status." (PMID 27565572, 2016). "Our results indicate that breast cancer patients had 18-30% decreased expression of HADHA gene." (PMID 22240105, 2012). "Our meta-analysis showed an 18.4%-26% reduction in HADHA expression in breast cancer." (PMID 22240105, 2012). "Also, there was an inconclusive but consistent under-expression of HADHA in subjects with metastatic and recurring breast cancers." (PMID 22240105, 2012). "Lastly, we examined the robustness of the differential expression of HADHA by conducting meta-analysis of published microarray studies comparing cases of breast cancer with subjects without breast cancer." (PMID 22240105, 2012). "Together these observations from published literature strongly support the biological plausibility of our finding that HADHA is differentially expressed in subjects with and without breast cancer." (PMID 22240105, 2012). "The HADHA gene [hydroxyacyl-CoA dehydrogenase/3-ketoacyl-CoA thiolase/enoyl-CoA hydratase (trifunctional protein), alpha subunit] was significantly under-expressed in breast cancer; more so in those with estrogen receptor-negative status." (PMID 22240105, 2012).